VWDE (von Willebrand factor D and EGF domains)
Synonyms: FLJ14712
Tractability: Antibody: UniProt places it where antibodies can reach, with high confidence; UniProt predicts a signal peptide or a membrane-spanning region; its Gene Ontology location is reachable by antibodies, with medium confidence. PROTAC: ubiquitination databases record sites on it.
Gene: Protein-coding gene on chromosome 7 (12,330,201 to 12,403,941, reverse strand). Ensembl gene ENSG00000146530.
Subcellular location: Secreted
Subcellular location (Human Protein Atlas): Cytosol; Predicted to be secreted
Gene Ontology:
Molecular function: signaling receptor binding
Cellular component: cell surface; extracellular region
Genetic constraint (gnomAD): Loss-of-function variants: 160 observed, 142.05 expected, observed/expected ratio (o/e) 1.13, 90% interval 0.99 to 1.28. The upper end of that interval is the gene's LOEUF score, 1.28, which puts it in group 5 of 6, group 1 being the genes least tolerant of losing a copy. Missense variants: 2,060 observed, 1,769.1 expected, observed/expected ratio (o/e) 1.16, 90% interval 1.12 to 1.21. Synonymous variants: 684 observed, 619 expected, observed/expected ratio (o/e) 1.11, 90% interval 1.04 to 1.18.
Homologues: Orthologues: chimpanzee VWDE (98% identical), macaque VWDE (93% identical), pig VWDE (81% identical), dog VWDE (79% identical), guinea pig VWDE (70% identical), tropical clawed frog vwde (38% identical), zebrafish si:ch211-246m6.5 (9% identical). Paralogues in human: FBLN2 (11% identical), EYS (9% identical), FBLN1 (8% identical), EFEMP2 (6% identical), EFEMP1 (6% identical), FBLN5 (6% identical).
Diseases named in the same sentence as VWDE in open-access papers:
VWDE is named in the same sentence as 10 diseases in open-access papers, as found by Europe PMC text mining. Sharing a sentence is not in itself a finding about the gene and the disease. The quoted sentences say what the papers report.
anxiety disorder (1 paper, 2024). A category of psychiatric disorders which are characterized by anxious feelings or fear often accompanied by physical symptoms associated with anxiety. "For anxiety disorders, 18 SNPs are linked to genes including CAMKMT, ARPP19, SOCS5, TNS3, VWDE, TSHZ2, and others." (PMID 39165506, 2024).
breast carcinoma (1 paper, 2021). "A recent study showed that VWDE is a significant driver oncogene with a highly mutation prevalence in breast cancer." (PMID 35126454, 2021).
Breast hypertrophy (1 paper, 2025). The presence of hypertrophy of the breast. "Moreover, the most central gene in the purple module was VWDE (also present as an Emperor penguin unique TEG), which in humans, is associated with breast hypertrophy." (PMID 39415606, 2025).
coronary artery diseases (1 paper, 2022). "The function of VWDE (von Willebrand factor D and EGF domains) gene product is not yet known while previous GWASs discovered the risk alleles for frontotemporal dementia, depression, and coronary artery diseases in this gene." (PMID 36482414, 2022).
Stroke (1 paper, 2021). Sudden impairment of blood flow to a part of the brain due to occlusion or rupture of an artery to the brain. "One notable exception was a variant in the VWDE gene encoding von Willebrand factor D and EGF-domain–containing protein which was associated with early-onset stroke in both white and black individuals." (PMID 34828431, 2021).
viral myocarditis (1 paper, 2025). Myocarditis that is caused by an infection with a viral agent. "Secondly, we uncovered novel loci (e.g., RETREG1 and VWDE) and pathways, such as viral myocarditis and lipid metabolism, broadening the understanding of biological mechanisms underlying BIs." (PMID 40650217, 2025).
VWDE also shares sentences with these, for which no sentence is quoted: dementia (1 paper); depression (1); frontotemporal dementia (1); tumor (1).